KRAS (KRas proto-oncogene, GTPase)
Diseases named in the same sentence as KRAS in open-access papers (continued):
Sharing a sentence is not in itself a finding about the gene and the disease.
cancer (continued). "Cancer-derived Exos can activate transforming signaling pathways in recipients cells by transferring oncogenic proteins such as mutated Kirsten rat sarcoma viral oncogene homolog (KRAS) proteins or the epidermal growth factor receptor variant III." (PMID 28783104, 2017). "In conclusion, our meta-analysis demonstrated that KRAS mutation detected in cfDNA was a prognostic biomarker in cancer patients." (PMID 28796802, 2017). "The predominance of KRas mutations in cancer and the essential role of KRas in mouse development suggests that this is the most important isoform." (PMID 28117393, 2017). "We also demonstrated that targeting MEK and PI3K in combination with HDACs reduces the self-renewal of PDAC cells harboring the mutant KRAS allele (KRAS G12D) and blocks cancer metastasis in vivo." (PMID 28152508, 2017). "Cancer-associated mutations in KRAS (10–30%), EGFR (10%) and BRAF (3%) in NSCLC patients are common." (PMID 28806950, 2017). "Our analysis showed that KRAS mutation in cfDNA was associated with a poorer survival in cancer patients for overall survival (OS, HR 2.02, 95% CI 1.63–2.51, P<0.01) and progression-free survival (PFS, HR 1.64, 95% CI 1.27–2.13, P<0.01)." (PMID 28796802, 2017). "DNA methylation is among the best characterized epigenetic alteration linked to transcriptional silencing of TSGs in KRAS-mutated cancers." (PMID 29088821, 2017). "Since c-MET inhibitors are already in clinical development for the treatment of cancers of the lung, pancreas, or other organs in which KRAS mutations are also frequent, our findings suggest further interesting opportunities for combination therapy." (PMID 28807782, 2017). "These two pathways are frequently activated in cancer cells due to aberrant activation of RTKs and/or activating mutations in their downstream signaling molecules such as KRAS and BRAF." (PMID 28002807, 2017). "In 2012, the FDA approved a real time PCR companion diagnostic test for KRAS, Therascreen KRAS test, which is the first genetic test to guide the treatment of cancer." (PMID 28125617, 2017). "Multiple mutations are indicative of cancer cell aneuploidy, and this “polyclonality” of KRAS SNPs is a common feature in PDAC patients." (PMID 29657983, 2017). "For example, HKDC1 has been previously shown to correlate with KRAS signaling in cancer cells, where loss of mutated KRAS expression led to an increased HKDC1 expression." (PMID 28039486, 2017). "Receptor tyrosine kinase (RTK) signaling pathways are frequently activated in cancer cells due to mutations of RTKs and/or their downstream signaling proteins such as KRAS and BRAF." (PMID 28002807, 2017). "We observed that DRP1Ser616 phosphorylation was diminished in both cancer cell lines carrying KRAS mutations and wild-type control cell lines such as SW1222 upon treatment with 10 μM ICG-001 for 6 h." (PMID 29290987, 2017). "Mutations activating the KRAS oncogene drive human cancers affecting the pancreas, lung, colon, and other tissues." (PMID 28807782, 2017). "Like CRCs with BRAF mutations, KRAS-mutated carcinomas had an increased frequency of the mucinous feature." (PMID 28583095, 2017). "KRAS which is one of the most frequently mutated oncogenes has a role in many signal transduction pathways significant to different types of human carcinomas including colorectal, pancreatic and lung." (PMID 28102286, 2017). "Because mutant KRAS genes are major drivers of common cancers, standardized tests for mutations in KRAS are being developed and used in trials of tailored cancer therapies ("precision medicine")." (PMID 27684555, 2016).
cancer (continued). "Although the exact role of autophagy in tumor progression of RAS-mutated tumors is still under debate, autophagy seems to be dispensable for the growth and survival of KRAS-mutated cancer cell lines derived from human tumors." (PMID 27933272, 2016). "It strongly suggests that although KRAS status is important to explain the killing effect of vitamin C, there must be other mechanisms underlying its role in cancer." (PMID 27323830, 2016). "FOXM1 is a transcription factor that plays a key role in activating target genes at the G1/S transition, is linked to HH signaling in human cancers, including colorectal cancer, and is an effector of KRAS/BRAF signaling." (PMID 27863397, 2016). "While clinical data supporting this prediction are lacking, mechanistic model simulations are consistent with the role of KRAS mutations as dominant mechanisms of resistance in MAPK-dependent HER2+ cancers." (PMID 27035903, 2016). "Although KRAS is commonly mutated in human cancers, targeted therapies for these refractory cancers remain a major clinical challenge." (PMID 27193833, 2016). "The KRAS gene is frequently mutated in multiple cancer types, but it fell off the drug discovery radar for many years because of its inherent “undruggable” structure and undefined biological properties." (PMID 27793187, 2016). "In contrast, in KRAS-mutation-positive cancer cell lines, wild-type RAS signaling instead promotes proliferation and tumorigenesis." (PMID 27911940, 2016). "The siRNA-driven knockdown of KRAS was previously shown to cause apoptosis of KRAS mutant-expressing cancer cells." (PMID 27322423, 2016). "We have here identified a new approach to targeting KRAS-mutated cancers using the histone deacetylase inhibitor romidepsin." (PMID 27634878, 2016). "Human cancer cell lines bearing KRAS mutations tended to be more sensitive to either BI-2536 or fasudil than KRAS wild-type ones (P<0.01 or P<0.001, Student's t-tests)." (PMID 27193833, 2016). "Epigenetic mechanisms are linked to isoform-specific KRAS proteins, that drive different cancer programs by modulation of diverse downstream signaling pathways." (PMID 27028869, 2016). "Because of the frequency of KRAS mutations in human cancers considerable attention has been paid to targeting this oncogene." (PMID 26881434, 2016). "KRas is frequently mutated in multiple cancer types; identifying drugs to treat such cancers is a good therapeutic strategy." (PMID 27193833, 2016). "Since this signaling pathway is dependent upon the mutational status of KRAS, a gene that is commonly mutated in CRC, we ascertained the role of KRAS in the sensitivity of cancer cells to hyperthermia." (PMID 27187477, 2016). "Due to the poor prognosis for cancer patients with mutated KRAS, much effort has been spent on developing specific therapies for targeting oncogenic KRAS." (PMID 27857191, 2016). "Although c-Myc activation contributes to up to 70% of all human cancers, and KRas mutation occurs in more than 50% of all human cancers, drugs inhibiting these oncogenes are not yet available." (PMID 27465491, 2016). "It was striking to observe that cells derived from cancers that show high mutational rates for KRas, such as colon (HCT 116), lung (A549) and pancreatic (MiaPaca2) cancers, have high levels of expression of S100A10." (PMID 27351226, 2016). "The RASCAL II study concluded that there was a significant prognostic value in failure-free survival alone in patients with Dukes’ C cancer harboring a KRAS G12V mutation." (PMID 26887348, 2016).
cancer (continued). "This review addresses the historical background and experimental studies that led to the discovery ofKirsten Ras as an oncogene, the role of mutated KRAS in human carcinogenesis, and recent therapeutic studies of cancer cells with KRAS mutations." (PMID 27102293, 2016). "In particular, activating mutations at codon 61 occur more frequently than at codon 12 of HRAS and NRAS in most cancer types, in contrast to KRAS where a mutation at codon 12 is predominant." (PMID 26799184, 2016). "After examination of the mutation profile of this patient by using NGS Cancer Panel, one rare KRAS mutation was observed at A146T." (PMID 27121310, 2016). "Recently, it was shown that the combination of MEK inhibitor AZD6244 and AKT inhibitor MK2206 are effective in KRAS mutated cancers." (PMID 26821351, 2016). "In contrast, the two most highly mutated sites across cancer genomes in protein coding sequence are a known mutational hotspot in codon 12 of the KRAS gene; these sites carried substitutions in 257 and 67 tumors, respectively." (PMID 27490693, 2016). "The classic sites of missense mutations in KRAS genes found in human cancers are at G12, G13, and Q61." (PMID 27684555, 2016). "RAS proteins are important regulators of cell fate and up to 30% of all cancers have driving mutations in KRAS, HRAS or NRAS." (PMID 26771141, 2016). "Activating KRAS mutation is an intermediate event of colorectal tumorigenesis and was observed in approximately 50 % of colorectal adenomas and carcinomas." (PMID 27765040, 2016). "Phosphorylated ERK signal was detected in all 4-cell lines used in our experiments, suggesting that the ERK pathway plays an important role in cancer development in KRAS or BRAF mutated cells." (PMID 25706985, 2015). "The use of high-throughput sequencing for detecting KRAS mutations has been described and some providers have started to offer dedicated cancer sequencing panels." (PMID 25823645, 2015). "The plasma/tissue (p/t) ratio of SEPT9 methylation rate was significantly higher than the p/t ratio of KRAS mutation load, especially in early stage cancers (p=0.0108)." (PMID 25946211, 2015). "KRAS is mutated in 35%-40% CRC and mutation of the KRAS protooncogene is an early event in development of these cancers, exerting a strong influence on the growth of colonic polyps and early cancers." (PMID 26042813, 2015). "Here, we demonstrate that loss of Ptf1a leads to upregulation of genes associated with KRAS-dependency in human cancer cells." (PMID 26151762, 2015). "EGFR inhibitors have been widely used in anti-cancer therapy; however, they are inefficient in mCRCs harboring activating KRAS mutations, which remains an obstacle to the effective treatment of mCRC." (PMID 26418750, 2015). "We established two original models, KRAS-humanized yeast and KRAS-non-cancer colon cells and showed that expression of mutated KRAS up-regulates starvation-induced autophagy in both." (PMID 26418750, 2015). "The c.35G > A (p.Gly12Asp) KRAS mutation has been identified frequently in cancers from colon, pancreas, lung, biliary tract and ovary." (PMID 25928347, 2015). "The three multiplexed assays described here between them will identify the nucleotide changes in 95% of the cancer cases where the KRAS gene is mutated." (PMID 26413866, 2015). "Cancers bearing the KRAS G13D mutation are notable for their distinct clinical behavior relative to other oncogenic KRAS mutations." (PMID 26958611, 2015). "It is worth noticing that aggressive cancer cells that harbor KRAS or EGFR mutations secreted serglycin constitutively in elevated levels." (PMID 26581653, 2015). "Due to the complex patterns of interdependent driver mutations, cancer cells frequently become dependent on certain oncogenic signals such as for oncogenic KRAS in CRC." (PMID 26299805, 2015). "KRAS is the most commonly mutated oncogene in human cancers and is associated with poor prognosis and drug resistance." (PMID 25946136, 2015).
cancer (continued). "The somatic KRAS c.35G>A mutation is the most frequent KRAS mutation in human cancers according to the COSMIC database." (PMID 26521233, 2015). "Here, we demonstrate that KRAS-induced autophagy is associated with up-regulation of ERK phosphorylation during nutrient limitation conditions in a non-cancer colon NCM460 cell model, consistent with a pro-autophagic role of MEK/ERK signaling." (PMID 26418750, 2015). "KRAS mutations occur in one third of human cancers and cluster in several hotspots, with codons 12 and 13 being most commonly affected." (PMID 25705018, 2015). "In many human cancers, mutations in the KRAS or BRAF gene lead to activation of the RAS/RAF pathway, resulting in over-expression of its target MAPK1 (ERK)." (PMID 25303610, 2015). "KRAS gene mutation is known for inducing constitutive activation of KRAS and stimulating cancer growth, and it is found in various organs, such as the colon, pancreas and lungs." (PMID 25936694, 2015). "The mouse PanIN-PDAC model provides a new experimental system to relate genetic changes in cancer, such as KRAS mutation, to epigenetic changes such as PTF1A downregulation." (PMID 26151762, 2015). "The n1046 mutation is homologous to the HRAS and KRAS mutations that are frequently found in human cancer cells." (PMID 25978500, 2015). "We have used commercially available primer probe assays for nine common KRAS mutations to design and optimize a multiplex assay approach to genotype KRAS mutant cancers using limited material using digital droplet PCR." (PMID 26413866, 2015). "Mutational data and gene expression data (pan-cancer normalized) are available for a limited number of patients only; nevertheless, KRAS activating mutations exhibited similar synergistic relationship with CIP2A expression levels as did high KRAS expression." (PMID 26278961, 2015). "Earlier studies have identified miRNAs that targeted components of the EGFR signaling pathway; however, few studies have explored the miRNA alterations in mutated KRAS tumors and their impact on cancer progression." (PMID 25756961, 2015). "In particular, activating (“gain-of-function”) mutations in HRAS and KRAS are among the most prevalent tumor initiating mutations found in human cancer cells." (PMID 25978500, 2015). "Mutation of KRAS oncogene is an early event in development of these cancers, exerting a strong influence on the growth of colonic polyps and early cancers." (PMID 26530529, 2015). "The four commonest mutations account for 80% of all KRAS nucleotide changes found in human cancers (85% of all changes in NSCLC), while the nine commonest mutations account for 95% of all changes and 97.5% of changes in NSCLC." (PMID 26413866, 2015). "High expression of CIP2A, NRAS, and to lesser extent KRAS was associated with poor prognosis in TCGA pan-cancer data set." (PMID 26278961, 2015). "Thereby, one hallmark mutation of pancreatic carcinoma, KRAS, mediates a shift in the cancer cell's glutamine-based energy supply system towards other pathways." (PMID 25595905, 2015). "Cancer cells harboring KRAS mutations bypass the Gln-dependent G1 checkpoint and instead are arrested in S-phase." (PMID 26682255, 2015). "Detection of KRAS hotspot mutations by ddPCR has been limited by the variety of potential alleles within adjacent loci, although some KRAS mutations occur more commonly in cancer than others." (PMID 26413866, 2015). "KRAS mutations are thought to occur early in the development of these cancers as they are found in benign, low malignant potential, and borderline tumors of mucinous histology." (PMID 27231561, 2015). "Oncogenic KRas mutations are present in about 30% of all human cancers and in more than 90% of pancreatic cancers." (PMID 26682255, 2015). "Knocking down the expression of wild-type Ras proteins, or reducing their activation by eNOS or SOS, inhibits cell viability, transformation, and/or tumorigenic growth of KRAS mutation-positive human cancer cell lines." (PMID 26452271, 2015).
cancer (continued). "Activating mutations in KRAS have been linked to several cancers, including pancreatic, ovarian, lung and colon." (PMID 26633513, 2015). "Our results therefore indicate that some forms of mutated KRAS up-regulate autophagy in non-cancer colon cells." (PMID 26418750, 2015). "Univariate logistic regression models identified the following factors as statistically significantly between KRAS codon 12 mutated carcinomas and WT carcinomas: gender, pN stage, pTNM stage and histological subtype." (PMID 25929517, 2015). "Twenty five subjects had synchronous carcinomas in both proximal colon and rectum, including 6 KRAS-mutated and 19 KRAS-wild type carcinoma." (PMID 25929517, 2015). "In the case of KRAS however, the vast majority of mutations are located on residues 12, 13 and 61 for both cancers." (PMID 24990767, 2014). "Our results are compatible with emerging data demonstrating that MEK inhibitors have promising antitumor activity in patients with KRAS-mutated cancer." (PMID 25313136, 2014). "Among the 46 cancer-related genes, KRAS and GNAS mutations were most frequently detected in both PDAC and IPMN cases." (PMID 24897499, 2014). "The high frequency (up to 30%) of RAS mutation in human cancers has stimulated the development of targeted agents against KRAS." (PMID 25313136, 2014). "Our laboratory developed an Activating KRAS Detection Chip and a WEnCA technique that can detect activated KRAS mutation status by screening circulating cancer cells in the surrounding bloodstream." (PMID 24884535, 2014). "The first example of a functional miRNA binding site mutation is a variant allele in the 3′-UTR of KRAS (rs61764370), a germline mutation found to disrupt let-7 binding, increase KRAS expression and predict cancer risk." (PMID 24732316, 2014). "RAS-activating mutations are present in 33% of all human cancers, whereby mutations in KRas are most prevalent and linked to the development of some of the most lethal cancers, including those of the lung, colon, and pancreas." (PMID 25328887, 2014). "KRAS is one of the genes that is often mutated in human cancer, and the mutation is associated with increased malignancy." (PMID 24952473, 2014). "The different metabolic states associated with different KRAS mutations will help in designing more efficacy cancer therapy, aimed at exploiting metabolic differences among KRAS mutations in NSCLC." (PMID 24952473, 2014). "Recently, an alternative model for KRAS mutation predominance in cancer was suggested on the basis of the likely relative protein expression levels of each isoform." (PMID 25109951, 2014). "An inflammatory response associated with KRAS/BRAF mutations has been reported in many human cancers, including CRC." (PMID 23755178, 2014). "For example, in cancer cells with a KRAS gene mutation, the inhibition of polo-like kinase 1 (PLK1) resulted in cell death." (PMID 24378760, 2014). "COSMIC database has shown that mutations in codons 12, 13 and 61 of the KRAS gene are known hotspots in various types of cancer." (PMID 25120700, 2014). "The clinical outcomes of patients with advanced cancer and KRAS mutations by type of codon and amino-acid substitution have not been systematically explored." (PMID 25313136, 2014). "The significance of the oncogene KRAS is underlined by frequently occurring activating mutations in numerous tumors and cancer cell lines." (PMID 24368337, 2014).